RARB (retinoic acid receptor beta)
Diseases named in the same sentence as RARB in open-access papers (continued):
Sharing a sentence is not in itself a finding about the gene and the disease.
breast carcinoma (continued). "The expression of RARB is usually low in breast cancers but it was observed to be high in KAIMRC1 cell." (PMID 29187162, 2017). "Retinoic acid (RA) significantly increases miR-10a expression as well the Retinoic Acid Receptor Beta (RARβ) in breast cancer cell lines (T47D and SK-BR-3)." (PMID 29077020, 2017). "In one of these examples, a predicted gain of an AP-1 binding site is observed upstream of the RARB gene in the breast cancer cell line MDA-MB-231, and this site co-localizes with a JUNB ChIP-seq peak (ChIP-seq performed in MDA-MB-231)." (PMID 28854983, 2017). "For instance, RARB is methylated in many breast cancer cell lines and treatment of these cell lines with a demethylating agent can restore inducibility of RARB by ATRA." (PMID 26929741, 2016). "Restoration of RARB gene expression in cervical cancer, breast cancer and lung cancer resulted in inhibition of cell growth and promotion of apoptosis." (PMID 27011326, 2016). "Breast cancer cells in which RARB was inhibited by siRNA continued to migrate after treatment with retinoic acid, indicating the inability of cells to respond on retinoic acid in the lack of RARβ receptor." (PMID 27011326, 2016). "RA enhances the COUP-TFII occupancy at Rarb promoter and leads to increased expression of RARβ target genes in breast cancer cells." (PMID 26110391, 2015). "In the present study, RARβ gene expression was significantly reduced in breast cancer tissues compared to healthy controls." (PMID 25934412, 2015). "In most breast carcinomas RARβ is downregulated by hypermethylation of its promoter and/or by alterations of chromatin structure." (PMID 25997921, 2015). "The levels of both RARβ and THRα gene expression were also found to be decreased in breast cancer patients compared to controls (p < 0.001)." (PMID 25934412, 2015). "Expression levels of RARβ and THRα were previously reported by this group, on a total of n = 100 breast tissues, consisting of n = 75 breast cancers, n = 10 fibroadenoma tissues and n = 15 normal breast tissues." (PMID 25934412, 2015). "Our study demonstrates that high concentrations of RA induce RARβ expression which mediates cell migration and cell motility inhibition in breast cancer cells." (PMID 24720764, 2014). "We have evaluated the RARβ protein expression in three breast cancer cells lines under basal conditions (MDA-MB231, T47D and MCF7)." (PMID 24720764, 2014). "Administration of retinoic acid (RA) in breast cancer cells induced RARβ gene expression that was greatest after 72 hrs with a concentration 1 μM." (PMID 24720764, 2014). "RARβ is necessary to inhibit migration induced by RA in breast cancer cells modulating the expression of proteins involved in cell migration." (PMID 24720764, 2014). "It has been observed an important reduction in RARβ mRNA expression in different types of human carcinomas including breast carcinoma." (PMID 24720764, 2014). "This study described a positive correlation between COUP-TFI expression and RARβ expression in various cancer cell lines including breast cancer, bladder cancer, and lung cancer cells." (PMID 24212637, 2011). "Previous studies using breast cancer cell lines have suggested that selective stimulation of RARβ increases NIS expression more efficiently than that of RARα." (PMID 21283523, 2011). "In MDA-MB231 breast cancer cells, the overexpression of COUP-TFI induced loss of anchorage-independent cell growth and enhanced the promoter activity of the RARβ gene." (PMID 24212637, 2011). "RARβ has been ascribed tumor suppressor-type activity and is often down regulated in breast cancer; it is inducible by atRA, and inducibility correlates with atRA sensitivity." (PMID 20696059, 2010). "A truncated, oncogenic RARβ protein (RARβ-prime) is exclusively expressed in breast cancer cell lines, and the presence of this isoform likely obstructs tumor suppressor functions of RARβ2 and RARβ4 protein isoforms." (PMID 16255778, 2005).
breast carcinoma (continued). "This case–control study aimed to determine the association between the promoter methylation ratio (PMR) of RARB and GSTP1 genes (separately and as a group) with breast cancer and its clinical‐pathological variables in Peruvian patients, using a liquid biopsy approach." (PMID 37548362, 2023). "The lack of association between methylation of RARB and breast cancer in Peruvian women does not support these claims." (PMID 37548362, 2023). "Previously, we have established that blocking the PAH2-mediated Sin3A interaction with SID-containing proteins using SID peptides or small molecule inhibitors (SMI) increased RARβ expression and induced retinoic acid metabolism in breast cancer cells, both in in vitro and in vivo models." (PMID 35406744, 2022). "In contrast, estrogen sensitizes human breast cancer cells to RA by inducing RARβ." (PMID 34419449, 2021). "The methylation of key genes related to breast cancer, like retinoic acid receptor beta (RARβ) and adenomatosis polyposis coli tumor suppressor (APC), has been associated with the presence of PAH adducts in breast tumor tissue and various sources of PAH exposure." (PMID 34203568, 2021). "Similarly to colon cancer, also in breast cancer the epigenetic silencing of the RARβ promoter was correlated to the hypermethylation of this DNA portion." (PMID 32012980, 2020). "The overlap between genes that were correlated with MR and those that were correlated with RARB was markedly greater in the normal breast than the overlap in breast cancer, and this was reflected in a more substantial overlap in the functional associations with the two NR in the normal breast." (PMID 33148314, 2020). "Other stromal genes dysregulated in AA women with breast cancer include Ras association domain-containing protein 1 (RASSF1A), Retinoic acid receptor beta (Retinoic acid receptor beta), Spermatogenesis associated 18 (SPATA18), and Sons of sevenless drosophila homolog 1 (SOS1)." (PMID 32824813, 2020). "RARB was detected above the threshold in 24% of breast cancers and MR was present in 71% of cases." (PMID 33148314, 2020). "Similarly, previous studies reported a significant correlation between RARβ expression and esophageal cancer, non-small-cell lung cancer, endometrial cancer, and breast cancer." (PMID 30944670, 2019). "Furthermore, silencing of the RARβ gene by promoter hypermethylation is frequently observed in metastatic lung, brain, and bone lesions compared with primary breast cancer." (PMID 30944670, 2019). "RARβ is a known tumour suppressor in breast cancer, confirmed in both cell line and animal models." (PMID 25934412, 2015). "For example, RASSF1A, CDH13 and RARβ have been reported to be frequently methylated in breast cancer (average frequency of 71 %, 49 % and 21 % respectively), which is similar to our results of 64 %, 51 % and 19 % methylation in both ipsilateral and contralateral pairs respectively." (PMID 26452468, 2015). "Mice of both genotypes were followed up for more than 12 months and no mammary tumors were identified, suggesting that RARβ deficiency alone does not promote mammary carcinogenesis." (PMID 25997921, 2015). "According to the depicted representative data from previous studies, RARB expression is thought to be associated with cellular sensitivity to retinoid in numerous cancer cells, including HNSCC cells, breast cancer cells, lymphocytic leukemia, and lung cancer cells." (PMID 25197641, 2014). "Our results indicate that RA may play a significant role in breast cancer development and progression modulating cellular migration and cytoskeletal reorganization via RARβ." (PMID 24720764, 2014).
breast carcinoma (continued). "The expression of RARβ protein varies among breast cancer cell lines." (PMID 24720764, 2014). "For example, TWIST1 and RARB methylation was used to detect breast cancer cells in ductal lavages." (PMID 22570110, 2012). "This hypothesis is supported by the observation that introduction of RARβ gene into breast cancer cell lines restored RA responsiveness to growth inhibition and induction of apoptosis." (PMID 19442290, 2009). "However, this could be seen to contradict other evidence suggesting that RARβ is a tumour suppressor gene that inhibits breast cancer migration and growth." (PMID 33148314, 2020). "Therefore, we hypothesize that RA reduces moesin, FAK and c-Src expressions in breast carcinoma MCF7 cell lines by RARβ." (PMID 24720764, 2014). "Due to the hierarchical transcriptional regulation by RARβ in embryogenesis and development, we hypothesized that multiple regulatory pathways, direct or indirect, could be mediated by overexpression of RARβ2 in breast cancer cells." (PMID 16255778, 2005). "It is more likely to express the hypermethylation of RARβ and APC in the promoter regions in breast cancer tissue in comparison to normal breast tissue." (PMID 37391844, 2023). "PMR of RARB and GSTP1 genes were obtained from blood plasma cfDNA of 58 breast cancer patients and 58 controls from Oncosalud‐Auna and INEN." (PMID 37548362, 2023). "Among these, promoter methylation of RARB and GSTP1 genes has shown the potential to be used as breast cancer biomarkers." (PMID 37548362, 2023). "Tumor suppressor genes like RARB and GSTP1 have been reported as hypermethylated in breast cancer tumors compared with normal tissues in several populations." (PMID 37548362, 2023). "Using human breast cancer cells transfected with MAD1 SID or treated with the MAD SID peptide, we observed a dissociation of MAD1, RARα and RARβ from Sin3A in a coimmunoprecipitation assay." (PMID 35406744, 2022). "Breast cancer cases from the METABRIC dataset were classified into four sample subgroups based on the expression of MR and RARB." (PMID 33148314, 2020). "Using the METABRIC breast cancer microarray dataset, we first examined the expression levels and degree of variance of MR, RARA, RARB and RARG in the cohort." (PMID 33148314, 2020). "As RARα mediates the anti-proliferative action of ATRA in breast cancer cells, we exposed SK-BR-3 cells to ATRA, AM580 (RARα-agonist), UVI2003 (RARβ-agonist) and BMS961 (RARγ-agonist)." (PMID 32384653, 2020). "Some methylation markers commonly used for monitoring breast cancer, including APC, RASSF1A, and RARβ, predominantly displayed patterns consistent with homogeneous methylation." (PMID 30154364, 2018). "Our results support the role of combinatorial ClF and EGCG or genistein exposures in regulation of transcriptional activity of DNA methylation-silenced tumor suppressor genes, such as RARB and PTEN, which seem instrumental in breast cancer development." (PMID 30544666, 2018). "For example, methylation of RARRES1 correlates with RARβ promoter methylation in prostate cancer and treatment of colon and breast carcinoma cells with AZA induced a demethylation of the RARβ promoter region and a restoration of RARβ expression." (PMID 29169400, 2017). "The most common biomarker candidates for detection of breast cancer from serum is RASSF1A gene, with 100 % specificity and 75 % sensitivity, and RARβ with 94 % specificity and 87 % sensitivity." (PMID 26421063, 2015). "PPARγ and RXR form a complex with βRARE in the RARβ promoter, and the combination of ligands of PPARγ and RXR was reported to induce RARβ in ATRA-resistant breast cancer cells in the presence of histone deacetylase inhibitor." (PMID 22685453, 2012). "The genes CD44 (P = 0.050), RARB (P = 0.026), ATM (P = 0.017) and STK11 (P = 0.040) also showed less frequent methylation in male breast cancer." (PMID 22765268, 2012).
breast carcinoma (continued). "Indeed, in both cell cultures and mouse models of mammary tumors, ATRA-induced growth inhibition is recapitulated only by the RARα agonist AM580, as RARβ and RARγ agonists are generally ineffective in terms of anti-proliferative effects." (PMID 38360674, 2024). "To establish whether ATRA modulates the expression of RARα, RARβ and RARγ, we exposed six TNBC and six retinoid-sensitive Luminal breast cancer cell lines to ATRA (1 μM) for 24 h." (PMID 33081033, 2020). "Indeed, the expression of RARβ’ in MCF-7 breast cancer cell line induced the ATRA resistance, while the expression of the full RARβ in both MCF-7 and MDA-MB-231 resulted in ATRA sensitivity." (PMID 32012980, 2020). "In standard growth conditions, no breast cancer cell line shows detectable levels of the RARβ transcript or protein regardless of the basal or luminal phenotype." (PMID 33081033, 2020). "We have also shown that ATPR could induce apoptosis via RARβ/RXRβ heterodimers and activation of ER stress involving the MAPK pathway in the breast cancer MDA‐MB‐231 cells." (PMID 32391634, 2020). "Some studies have shown that decreased or absent RARβ expression correlates with an increase in metastatic processes in various tumor types, including breast cancer and cancers of the digestive tract." (PMID 30944670, 2019). "The mechanism through which stromal RARβ achieves its tumor-promoting effect probably involves the production of CXCL12/SDF-1 in stroma cells and the consequent activation of the Src-ErbB2-Akt signaling pathway in the breast cancer cells." (PMID 31590252, 2019). "Furthermore, Feng and colleagues (2007) analyzed the methylation of multiple genes in breast cancer using bisulfite pyrosequencing and found that RASSF1 was methylated in 58 % of breast tumors, CDH13 in 44 % and RARB in 17 %." (PMID 27065772, 2016). "Methylation-sensitive high-resolution melting was used to screen promoter methylation in a panel of 13 genes reported as methylated in breast cancer (RASSF1A, TWIST1, APC, WIF1, MGMT, MAL, CDH13, RARβ, BRCA1, CDH1, CDKN2A, TP73, and GSTP1) in 29 tumour pairs (16 ipsilateral and 13 contralateral)." (PMID 26452468, 2015). "Moreover, promoter regions of candidate genes like GSTP1 and RARB are hypermethylated in most patients with breast cancer, regardless of the cancer stage." (PMID 37548362, 2023). "All-trans retinoic acid (ATRA), a known pan-retinoic receptor agonist, has been found to regulate EMT and inhibit migration in breast cancer via the TGF-β pathway, a notion that might support the use of RARB agonists against poorly differentiated HCC with TGF-β-dependent EMT features." (PMID 32517019, 2020). "In contrast to nontumorigenic MCF12A and non-invasive breast cancer cell line T47D, TET2 was predominantly localized in the cytoplasm in aggressive triple-negative breast cancer cell line MDA-MB-231, which is deficient in endogenous RARβ expression." (PMID 31590252, 2019). "did not detect RARβ expression in five breast cancer cell lines and showed that the treatment with RA could induce its expression." (PMID 24720764, 2014). "DNA promoter methylation of a gene panel including APC, CCND2, RARB, RASSF1A, and SCGB3A1 in breast cancer samples was not correlated with age in a previous study." (PMID 27028854, 2016). "As for RARβ, its expression does not seem to be important for ATRA anti-tumor activity in breast cancer." (PMID 25888236, 2015). "A three-day treatment with caffeic acid (1 – 50 mM) and chlorogenic acid (1 – 20 mM)decreases the methylation-specific band for the retinoic acid receptor beta(RARB) but does not significantly change global DNA methylationin MCF-7 and MDA-MB-231 human breast cancer cells." (PMID 32644097, 2020).
lung carcinoma (57 papers, 2003 to 2026). "In the paper of Suh and co-workers the explanation of the loss of RARβ expression in some lung cancer cell lines was attributed to epigenetic silencing as histone H3 acetylation and hypermethylation of the RARβ promoter." (PMID 32012980, 2020). "The loss of RARβ mRNA expression has been observed in many lung cancer cells lines and its expression is influenced from intracellular concentration of retinoids, mediated by CRBP-1." (PMID 32909215, 2020). "In our study, increasing RARB methylation was associated with more aggressive subtypes of lung cancer and also increased with tumor grade (both p<0.001)." (PMID 29851970, 2018). "The loss of coactivators, such as AF2 co-activators of the RAR-Thyroid Hormone Receptor complex are often lost in human lung cancer and the loss of AF-2 cofactors results in low levels of transcribed RARβ." (PMID 28008143, 2017). "Retinoic acid receptor β is believed to promote transcription of tumor suppressor genes and has been found to be decreased in many preneoplastic lung cancers; therefore, decreased expression of RARβ has been suggested as a biomarker for lung cancer risk." (PMID 26462767, 2015). "The loss and reduction of RARβ expression have been reported in a large percentage of patients with lung cancer." (PMID 25806093, 2015). "The loss of RARβ expression due to hypermethylation is of interest as are bronchial premalignant lesions in developed lung cancer." (PMID 18625040, 2008). "The loss of RARβ mRNA expression has been observed in many lung cancer cell lines also suggesting that to function as a tumor suppressor gene, RARβ expression is contingent on the intracellular concentration of retinoids." (PMID 18625040, 2008). "However, RARβ and perhaps also RARγ and RXRβ were repressed in a high proportion of lung cancer patients, suggesting the association of lung carcinogenesis with the loss of expression of one or more receptors." (PMID 35631448, 2022). "The first observation that several lung cancer types are characterized by the loss of the short arm of chromosome 3p, where the RARβ gene is localized, led to the investigation of retinoic acid receptors functionality in relation to the different responsiveness to retinoic acids’ treatments." (PMID 32012980, 2020). "Because many studies suggest a tumor suppressor role for RARβ and reduced RARβ expression is found in about 45-50 % of lung cancers, the decreased expression of RARβ observed in this study suggests a greater risk for development and/or promotion of lung cancer." (PMID 26462767, 2015). "Seven tumor suppressor genes (CDKN2A, CDH13, MGMT, MIR137, DAPK1, RARB, and RASSF1A) consistently exhibited hypermethylation in both lung cancer and in association with smoking exposure." (PMID 42073597, 2026). "The pattern ‘CEGCKGFF’ appeared in 10% of lung cancer cases, specifically in the proteins RARB and VDR, and was also found in NR1I2 and PPARG within the treatment dataset." (PMID 40334012, 2025). "Inducing the expression of RARβ has also been shown to inhibit the carcinogenesis of some squamous cell tumors, including lung cancer, esophageal cancer, and breast cancer." (PMID 37644077, 2023). "In another study, elevated levels of RARβ methylation were observed in two of the seven lung cancer cells, and treatment with 5-aza-2’-deoxycytidine restored retinoic acid responsiveness (29%)." (PMID 35631448, 2022). "RARβ is one of the RARs which has tumor-suppressive properties and is found to be underexpressed, with RARβ hypermethylation being the major reason in lung cancer subjects." (PMID 35631448, 2022). "When ciglitazone was combined with SR11237, it significantly increased RARβ expression in lung cancer cell lines, which was diminished by a PPARγ-selective antagonist, bisphenol A diglycidyl ether." (PMID 35631448, 2022).